IL1B (interleukin 1 beta)
Diseases named in the same sentence as IL1B in open-access papers (continued):
Sharing a sentence is not in itself a finding about the gene and the disease.
airway hyperresponsiveness (18 papers, 2005 to 2025). "We have previously shown that high fat diet (HFD) for 2 weeks increases airway hyperresponsiveness (AHR) to methacholine challenge in C57BL/6J mice in association with an increase in IL-1β levels in lung tissue." (PMID 30670753, 2019). "Studies indicate that PFAS exposure can activate inflammasomes in bronchial epithelial cells, leading to the release of pro-inflammatory cytokines (IL-1β, IL-18, and IL-33) and airway hyperresponsiveness." (PMID 41150549, 2025). "We did this by stimulating airway fibroblasts with a 1 ng/ml dose of recombinant IL-1α, IL-1β or IL-33 for 24 hours and then assessed the release of inflammatory mediators known to be involved in chronic inflammation, and airway hyperresponsiveness in asthma." (PMID 32457454, 2020). "IL-1RA can bind the IL-1 receptor to block the activity of the IL-1β signaling pathway and ameliorate eosinophil infiltration, airway hyperresponsiveness, Th2 cytokine levels in bronchoalveolar lavage fluid, and airway remodeling in asthmatic mice." (PMID 29254155, 2017). "The present study demonstrates that long-term exposure of IL-1β increased the contractile response to 5-HT reflecting the development of airway hyperresponsiveness." (PMID 17407556, 2007). "Oxidative stress induced by IgE challenge leads to the activation of genes for many pro-inflammatory cytokines, including IL-1β, which plays an important role in airway hyperresponsiveness and this not only in man but likely even in heaves." (PMID 16164745, 2005). "We hypothesized that airway sensitization might induce an oxidative stress and increase the ROS production, which in turn might enhance a production of IL-1β and airway hyperresponsiveness." (PMID 16164745, 2005). "We have hypothesized that equine airway sensitization might induce an oxidative stress and increase the ROS production, which in turn might enhance a production of IL-1β and airway hyperresponsiveness." (PMID 16164745, 2005). "It is not a surprise that the increase in IL-1β mRNA expression was linked to an increase in airway hyperresponsiveness." (PMID 16164745, 2005). "Furthermore, obese mice treated with IL-1β antagonist could attenuate airway hyperresponsiveness and inflammtion of lung." (PMID 29254155, 2017). "infections have been shown to induce responses with increased IL-1β, NLRP3, and caspase-1, that drive steroid-resistant neutrophilic inflammation and airway hyperresponsiveness." (PMID 41156007, 2025). "Neutrophils also secrete cytokines and chemokines, such as IL-1β, TNF-α, CXCL8 (IL-8), and GM-CSF, which further enhance the inflammatory response leading to chronic inflammation, airway hyperresponsiveness and, in a longer perspective, airway remodeling." (PMID 41156007, 2025). "Activation of the NLRP3 inflammasome with production in the pro-inflammatory cytokine IL-1β and neutrophil extracellular trap (NET) formation drive steroid-resistant neutrophilic inflammation and airway hyperresponsiveness in allergic airway diseases." (PMID 36385161, 2022). "The main finding of our study was that, in mice on a high fat hypercaloric diet, caloric restriction prevented the development of airway hyperresponsiveness and upregulation of IL-1β gene expression in lung parenchyma, regardless of the diet." (PMID 30670753, 2019). "IL-1β induces murine airway hyperresponsiveness, via a non-transcriptional up-regulation of 5-HT2A receptor-mediated contractile response." (PMID 17407556, 2007). "To summarize, the present study demonstrates that IL-1β can induce murine airway hyperresponsiveness, via a non-transcriptional up-regulation of 5-HT2A mediated contractile response through an alteration of the MAPK pathways." (PMID 17407556, 2007).
airway hyperresponsiveness (continued). "The present study was designed to investigate if IL-1β could be involved in the development of airway hyperresponsiveness and if transcriptional mechanisms, epithelium contractile factors and mitogen-activated protein kinase (MAPK) pathways are involved in IL-1β effect." (PMID 17407556, 2007).
alcoholic liver diseases (18 papers, 2013 to 2026). A disorder caused by damage to the liver parenchyma due to alcohol consumption. "In patients with alcoholic liver disease or non-alcoholic steatohepatitis, increased hepatic levels of inflammasome components together with increased serum levels of IL-1β have been reported and associated with liver damage in alcoholic liver disease." (PMID 31547621, 2019). "Notably, increased expression of inflammasome components (IL‐1β, IL‐18, Casp1) has been documented in patients with alcoholic liver disease and is associated with hepatic injury." (PMID 41583017, 2026). "It has been reported that both patient and animal model with alcoholic liver disease, the levels of IL-1β are significantly increased in the liver and the serum." (PMID 32143357, 2020). "Elevated levels of the pro-inflammatory cytokines TNF-α, IL-1β, and IL-8 have been observed in alcoholic liver disease patients." (PMID 30052665, 2018). "The ensuing expression of pro-inflammatory cytokines (e.g., tumor necrosis factor α [TNFα], interleukin [IL]-8, and IL-1β) results in cellular dysfunction that contributes to alcoholic liver disease (ALD)." (PMID 26695748, 2015). "IL-1β and TNFα are factors that promote alcoholic liver disease and NASH through NF-κB activation." (PMID 25470242, 2014). "The results from the present study prompted us to hypothesize the preventive or therapeutic potential of NTP on alcoholic liver disease and non-alcoholic fatty liver disease in which IL-1β and TNFα play an important role in disease progression." (PMID 25470242, 2014). "Alcoholic liver disease stimulates the release of cytokines, such as TNF-α, interleukin-1β (IL-1β) and IL-6, which promote the production RANKL and osteoclastogeneis." (PMID 32151025, 2020). "Additionally, polymorphisms in the genes encoding the IL-1R antagonist (IL-1ra; Il1rn) and IL-1β (Il1b), but not IL-1α (Il1a) and IL1-R1 (IL-1R1 type 1; Il1r), have been associated with a susceptibility to alcoholism or ALD (alcohol liver disease) in Spanish men." (PMID 25852553, 2015).
chronic gastritis (18 papers, 2010 to 2025). Inflammation of the stomach that is chronic in nature. "H. pylori infection causes chronic gastritis and induces an inflammatory response that increases the pro-inflammatory factors interleukins (IL-1β, IL-6, IL-8, IL-17), tumour necrosis factor α (TNF-α), interferon γ (IFN-γ), and C-reactive protein (CRP)." (PMID 38475712, 2024). "IL-1B and IL-1RNare associated with an increased risk for chronic gastritis and peptic ulcer disease." (PMID 30320011, 2018). "We aimed to determine if IL-1B+3954 and IL-1RN polymorphisms are associated with the risk of chronic gastritis and peptic ulcer in Iranian population." (PMID 30320011, 2018). "Frequency distribution in our population showed that IL-1B-511*C homozygote allele was most frequent in chronic gastritis group (58.8%)." (PMID 26401131, 2015). "The present study examined the role of IL1A and IL1B polymorphisms and the co-existence of H. pylori infection in the susceptibility to the development of chronic gastritis in group of patients from Western Poland." (PMID 23995914, 2013). "Analysis of association of IL1A and IL1B gene polymorphisms in H. pylori-infected patients with chronic gastritis was performed separately for each gene." (PMID 23995914, 2013). "In this study, we investigated whether IL-1B (rs1143634) and IL-1RN polymorphisms are associated with chronic gastritis or peptic ulcer in Iran." (PMID 30320011, 2018). "In DGC, Helicobacter pylori infection plays a central etiological role, initiating chronic gastritis and promoting an inflammatory milieu characterized by cytokines such as IL-1β, TNF-α, and IL-8, which contribute to mucosal damage and carcinogenesis." (PMID 40862793, 2025). "BAFF promotes elevated inflammatory factors such as IL-1β, IL-6, IL-23, and TGF-β in Helicobacter pylori-associated chronic gastritis." (PMID 35320937, 2022). "BAFF promotes the production of several inflammatory mediators in Hp-related chronic gastritis, including IL-1β, IL-6, IL-23, and TGF-β." (PMID 33324396, 2020). "In the context of such subjects, the effects of polymorphism in two cytokine genes, the pro-inflammatory cytokine IL-1B and anti-inflammatory cytokine IL-1RN, in relation to the development of peptic ulcer and chronic gastritis were analyzed." (PMID 30320011, 2018). "In the non‐infected chronic gastritis group, miR‐223 was also negatively correlated with IL1B mRNA expression (r = −0.52; p = 0.048)." (PMID 26945693, 2016). "Notably, levels of IL-1α, IL-1β, IL-6, and IL-12, which are the main contributors to human chronic gastritis, were decreased in Nrdc−/− mice." (PMID 28230087, 2017). "Immunohistochemical analysis allowed us to show expression and cell localization of TNF‐α, IL‐1β, IL‐2, IL‐12‐p40 and TGF‐β‐RII proteins in the normal mucosa, and in H. pylori infected and non‐infected chronic gastritis." (PMID 26945693, 2016). "IL-1B-511*T/T homozygous allele for cancer group had OR = 2.349 (95% CI: 0.583–9.462), heterozygous IL-1B-511*T had OR = 1.470 (95% CI: 0.583–3.709) and heterozygotes in TNF-A-308 genotype for chronic gastritis had OR = 1.402 (95% CI: 0.626–3.139)." (PMID 26401131, 2015). "Herein, we assessed whether H. pylori infection and its eradication, beyond its cagA virulence genotype, change the expression of inflammatory mediators (TNFA, IL6, IL1B, IL12A, IL2 and TGFBRII) in chronic gastritis patients." (PMID 26945693, 2016). "mRNA and protein expression of TNFA, IL6, IL1B, IL12A, IL2 and TGFBRII and miRNAs miR‐103a‐3p, miR‐181c‐5p, miR‐370‐3p, miR‐375 and miR‐223‐3p were evaluated in tissue samples from 20 patients with chronic gastritis H. pylori negative (Hp−) and 31 H." (PMID 26945693, 2016).
corneal infection (18 papers, 2011 to 2025). A viral or bacterial infectious process affecting the cornea. "Toll like receptors (TLR) and IL-1β are expressed in corneal ulcers caused by filamentous fungi, and mediate disease pathogenesis and bacterial killing in murine models of Pseudomonas keratitis." (PMID 23750216, 2013). "Considering that neutrophils are the primary source of IL-1β during MRSA corneal infections, we investigated if α-hemolysin induces neutrophil IL-1β secretion under defined in vitro conditions and if this is dependent on the canonical NLRP3 pathway." (PMID 41415470, 2025). "A role for neutrophil-derived IL-1β has also been demonstrated during corneal infection with the filamentous fungus A. fumigatus." (PMID 35406754, 2022). "qPCR detection of corneal ulcers from patients and infected epithelial cell lines revealed that the mRNA expression of Toll-like receptors, IL-1β, IL-6, and IL-8 was elevated." (PMID 35578336, 2022). "IL-1β is expressed within all corneal layers and has been detected in tears of patients with corneal infection and inflammation." (PMID 33208864, 2020). "IL-1β is necessary to induce chemokine expression, early in PA corneal infection, for recruitment of leukocytes to the site of infection." (PMID 28796783, 2017). "Mature IL-1β was undetectable before corneal infection, and induced comparably to 1200–1600 pg/ml in the Lum+/− and the Lum−/− infected corneas for up to 5 days after infection." (PMID 23358433, 2013). "However, during S. pneumoniae corneal infection, live bacteria appear to provide both the priming and inflammasome activation signals required to generate the cleaved form of IL-1β." (PMID 26877061, 2016). "Proinflammatory cytokines such as IL-1β and IL-6 contribute to corneal ulceration." (PMID 22219637, 2011). "The proinflammatory cytokine interleukin (IL)–1β is present in the tear fluid of individuals with corneal diseases such as bacterial keratitis and corneal ulcer as well as those with corneal chemical burns, and it contributes to the activation of corneal fibroblasts." (PMID 22219637, 2011). "However, the contribution of IL-1β to P. aeruginosa pathogenesis could be dependent on the infection model, as IL-1β has been shown to promote bacterial clearance during corneal infection with P. aeruginosa." (PMID 30455194, 2019). "An mRNA analysis of 110 patients with corneal ulcers showed heightened expression of NOD-like receptor protein 3 (NLRP3) and increased levels of inflammatory cytokines such as interleukin-1β (IL-1β), IL-8, and IL-17." (PMID 38533385, 2024).
eosinophilia (18 papers, 2011 to 2025). "Necrotic liver injury can induce massive eosinophilia, accompanied by caspase-1-mediated eosinophil pyroptosis, degranulation, and IL-1β/IL-18 secretion." (PMID 39611173, 2024). "IL-1β plays an important role in asthmatic inflammation, contributing to eosinophilia, IgE switching, and Th2 inflammation." (PMID 39611173, 2024). "The activation of T lymphocyte and eosinophilia with increased peripheral proinflammatory cytokines IL-1β, IL-6 and TNF-α are identified as the main features of FD." (PMID 36091013, 2022). "Here, we demonstrated the direct contribution of STR, especially T1R3, to the regulation of macrophage IL‐1β production and eosinophilia in CRS using gurmarin, T1R3 deletion, and STR overexpression." (PMID 35988262, 2022). "We investigated the therapeutic effects of trehalose and saccharin on macrophage IL‐1β production and eosinophilia in the mouse model of ECRS with myeloid cell‐specific autophagy‐related gene 7 (Atg7) deletion." (PMID 35988262, 2022). "It reduces pulmonary responses to antigen, tissue eosinophilia and IL-5 expression in inflammatory cells and decreases elevated levels of IL-1β and IL8 in viral upper respiratory tract infections." (PMID 35359601, 2022). "The increased ILC2 expansion in IL-1β−/− mice correlated with increased early IL-5 and IL-13 cytokine production, helminth-induced eosinophilia and goblet cell hyperplasia." (PMID 23935505, 2013). "Although more and more of the previously identified risk factors can be linked with the other phenotypes, ARAD (neutrophilia, IL-1β, IL-8, IL-6, and TNF-α, CRP) and RAS (eosinophilia, CRP), protein profiles observed in this and previous reports 27 do not show significant changes." (PMID 24750386, 2014). "In this regard, our results of eosinophilia regulation by the STR agonists via a preferential effect on macrophage IL‐1β production may provide an alternative therapeutic modality to alleviate ECRS, particularly prior to its progression to severe and recurrent CRSwNP." (PMID 35988262, 2022). "Collectively, our results suggested a therapeutic efficacy of trehalose in alleviating eosinophilia and CRS via suppression of inflammatory responses entailing macrophage IL‐1β in an autophagy‐independent manner." (PMID 35988262, 2022). "In addition to increased NO levels and arginase activity, coinfected mice presented a classic Th2 anti-Sv response: eosinophilia, higher levels of alternate activated macrophages (M2), increased concentrations of CCL24 and IL-4, and lower levels of IL-1β." (PMID 37888224, 2023). "Activation of sweet taste receptor but not autophagy contributed to the alleviation of eosinophilia and IL‐1β dysregulation." (PMID 35988262, 2022). "Progesterone, on the other hand, significantly increases the expression of IL-10, IL1-β, and TNF-α in the lungs, and augments the release of IL-4 by bone marrow cells, which may lead to eosinophilia." (PMID 21639909, 2011). "In addition, given trehalose as a naturally‐occurring sugar with less sweetness than sucrose, we found anti‐inflammatory effects of diverse STR agonists, especially saccharin, on macrophage IL‐1β production and eosinophilia in CRS regardless of dysfunctional autophagy." (PMID 35988262, 2022). "The stronger increase in ILC2 numbers in the absence of IL-1β following Hp infection could be confirmed by pharmacological blockade with Anakinra, and Anakinra treated mice additionally exhibited increased eosinophilia and IL-5 and IL-13 cytokine levels." (PMID 23935505, 2013). "However, the absence of eosinophilia and allergen-specific IgE in our patients suggests that this immune profile may differ from classical atopy and instead involve innate immune activation through lipid-mediated pathways (e.g., IL-1β/IL-23 axis)." (PMID 41346588, 2025).
Hyperinsulinemia (18 papers, 2010 to 2025). An increased concentration of insulin in the blood. "Plasma IL-1Ra associated with plasma IL-1β (r=0.40), and more strongly with hyperinsulinemia and IR than apoB, while the association of plasma IL-1β was limited to second phase and total insulin secretion (r=0.23)." (PMID 26417659, 2015). "APP/PS1 mice were also characterized by significant hyperinsulinemia (P < 0.01) and modest increases in the levels of IL-1β (P < 0.05)." (PMID 34393764, 2021). "The altered microbiome was associated with increased levels of IL6 in the serum, Claudin-2, IL6, and IL1β in the distal intestine with concurrent inflammatory lesions in the liver and hyperinsulinemia." (PMID 32927823, 2020). "SREBP2 protein levels are elevated in human NASH, possibly due to a direct stimulatory effect of hyperinsulinemia and high levels of circulating and hepatic IL-6 and IL-1β." (PMID 29522534, 2018). "Insulin resistance (IR) and compensatory hyperinsulinemia characterize prediabetes, and the involvement of an activated interleukin-1 (IL-1) family, mainly IL-1β and its receptor antagonist (IL-Ra), is well documented." (PMID 26417659, 2015). "HFD-fed CadKO males showed reduced proinflammatory adipocytokines (TNFα, IL1β, IL6), thus reducing inflammation, macrophage infiltration, and hyperinsulinemia." (PMID 37443781, 2023). "In a recent manuscript, it was reported that IL-1β produced by macrophages inside Langerhans islets in response to strong infection was not sufficient to induce hyperinsulinemia; a systemic surge of IFNγ was also required." (PMID 39107476, 2024). "Notably, infection with a high viral dose lowered blood glucose levels, which was dependent on cytokines such as IL-1β, IL-1α, IFNγ and TNF and proposed to be the result of hyperinsulinemia." (PMID 39107476, 2024). "Rosiglitazone treatment reduced hyperinsulinemia (DIO 4510 +/− 490 pg/ml: DIO-Rosi 2170 +/− 620 pg/ml), serum CCL2 levels (DIO 84.2 +/− 0.18 pg/ml: DIO-Rosi 47.3 +/− 4.6 pg/ml) and SVF mediator production of IL-6, TNFα, IL-1β and IL-10." (PMID 20445733, 2010).